PPARG (peroxisome proliferator activated receptor gamma)
Diseases named in the same sentence as PPARG in open-access papers (continued):
Sharing a sentence is not in itself a finding about the gene and the disease.
diabetes (continued). "Activation of peroxisome proliferator-activated receptors (PPARs), and particularly ofPPARα and PPARγ, using selective agonists, is currently used in the treatment of metabolic diseases such as hypertriglyceridemia and type 2 diabetes mellitus." (PMID 19325917, 2009). "Over the last decade, PPARγ has emerged as an important drug target in type 2 diabetes mellitus, and TZDs are widely used for treatment of diabetic patients." (PMID 19587804, 2009). "More importantly none of the research subjects used was diabetic where the steroidogenic effect of diabetes is an important component for evaluation of TZDs-PPARγ activators." (PMID 19536350, 2009). "Rosiglitazone, an agonist for the nuclear receptor peroxisome proliferator-activated receptor gamma (PPARγ), is a widely used drug for the treatment of type 2 diabetes mellitus." (PMID 19243600, 2009). "There is now strong experimental evidence to support the theory that PPARγ inhibits diabetes-induced retinal leukostasis and leakage, playing an important role in the pathogenesis of diabetic retinopathy." (PMID 18309374, 2008). "Thiazolidinediones, an FDA approved class of anti-diabetic drugs, are highly selective activating ligands for PPARγ at doses used to treat diabetes." (PMID 18237383, 2008). "There are reasons to beencouraged in targeting PPARγ in a chemoprevention context as studieson the consequences of long-term usage TZDs in diabetes patients have revealeda protective benefit against lung cancer." (PMID 18528521, 2008). "It is worth noting that mostof the studies use low doses of TZDs which are sufficient to activate PPARγ and control diabetes." (PMID 18784849, 2008). "It is clearthat substantial experimental and clinical research is still needed to clarifythe role of PPARγ in the whole body physiology and thepathophysiology of various diseases such as diabetes, obesity, hypertension,atherosclerosis, and cancer." (PMID 19277201, 2008). "Evidence of both pro-carcinogenic and anti-tumorigenic effects of PPARγ agonists have been mainly studied in vitro and in vivo models that do not take into full account the metabolic characteristics of patients with diabetes." (PMID 17584937, 2007). "Over the last decade, the gamma subtype of the peroxisome proliferator-activated receptors (PPARγ), has emerged as an important drug target in diabetes." (PMID 17584937, 2007). "Drugs that activate PPARγ, such as the thiazolidinediones (TZDs), are widely used for treatment of Type 2 diabetes mellitus." (PMID 17584937, 2007). "Additionally, proteomics analysis further revealed that polyphenols downregulate multiple inflammatory factors via the PPARγ/NF-κB axis, providing a clean basal microenvironment for diabetes." (PMID 41504281, 2026). "We then examined whether the expression of HMGA2, PPARG, ADIPOQ and IL6 was associated with diabetes remission." (PMID 40740163, 2025). "However, when selective PPARγ agonist rosiglitazone (RSG) was used for treating diabetes, it had adverse cardiovascular effects, such as stimulating cardiac hypertrophy and oxidative stress that are independent of cardiomyocyte PPARγ." (PMID 41515974, 2025). "Synthetic agonists of PPARγ have been used to treat diabetes mellitus for decades." (PMID 40119175, 2025). "Furthermore, MR409 prevented the diabetes-mediated downregulation of the anti-aging protein Klotho and PPARγ expression." (PMID 40926987, 2025). "Additionally, pioglitazone—a PPARγ agonist approved for diabetes—has demonstrated the ability to reduce tumor size and prevent metastasis in animal models of PAX8/PPARγ fusion-positive FTC, with preliminary clinical evidence supporting its use [NCT01655719]." (PMID 41590496, 2025). "Pioglitazone is a selective PPARγ agonist and is used clinically for the treatment of diabetes, suggesting that it may become a candidate drug for the clinical treatment of ALSV infection." (PMID 39655955, 2025).
diabetes (continued). "If proven, the potential of thiamine to activate PPARγ could revolutionize diabetes treatment by offering a safer alternative to current PPARγ agonists, with fewer side effects." (PMID 41368574, 2025). "The therapeutic landscape for NRs has expanded with the approval of drugs like PPARγ agonists (pioglitazone, rosiglitazone) for diabetes, FXR agonists (obeticholic acid) for liver diseases, and selective TR agonists (resmetirom) for Metabolic dysfunction-Associated Steatohepatitis (MASH)." (PMID 40926269, 2025). "PPARγ is an important target in the metabolic and inflammatory processes of diabetes." (PMID 40003935, 2025). "Given that PPARγ agonists are clinically approved drugs for dyslipidemia and diabetes, this class of agents may represent a promising new therapeutic approach for gallbladder cancer management." (PMID 41403929, 2025). "In addition, PPARγ agonists can effectively treat diabetes and lipid metabolism disorders as insulin sensitizers." (PMID 41011216, 2025). "We previously reported changes in HDL and LDL subclasses distribution in diabetes patients treated with a PPARγ agonist, thereby supporting the presumption that PUFAs could affect lipoproteins’ structure and functionality by acting as PPAR ligands." (PMID 39199290, 2024). "Subsequently, we selected IL6, AKT1 and PPARG as core targets for the treatment of diabetes." (PMID 39707185, 2024). "Among the antidiabetic medications, synthetic peroxisome proliferator-activated receptor γ (PPARγ) agonists (e.g. thiazolidinediones, TZDs or glitazones) represent the most considerable example of how improving AT function is beneficial for diabetes management." (PMID 38642584, 2024). "Suppression of PPARγ induces diabetes implicating an adverse effect of MG of enhancing DM severity." (PMID 39413106, 2024). "This miRNA seems to be involved in the pathogenesis of diabetes and lipopolysaccharide injury, but more intriguingly, its downregulation has been reported to be involved in the activation of NF-kB signalling and the PPARγ pathway." (PMID 39300590, 2024). "In addition, PPARG agonists, known as thiazolidinediones, are well established in the treatment of type 2 diabetes mellitus." (PMID 38378472, 2024). "In the treatment of diabetes, one strategy is the development of selective PPARγ modulators, SPPARMs, to preserve the expression level of PPARγ in vivo and regulate the transcription of therapeutic-related target genes while avoiding the regulation of target genes linked to adverse reactions." (PMID 38719955, 2024). "Moreover, the PPARγ pathway is involved in the development of different diseases, such as type 2 diabetes mellitus (DM2), cancers, skin irritation, and inflammation." (PMID 38791533, 2024). "Thiazolidinediones (TZDs) including rosiglitazone and pioglitazone function as peroxisome proliferator-activated receptor gamma (PPARγ) full agonists, which have been known as a class to be among the most effective drugs for the treatment of type 2 diabetes mellitus (T2DM)." (PMID 39459249, 2024). "Furthermore, this observation resonates with the superior efficacy of PPARγ agonist pioglitazone over sulfonylureas and metformin in patients with a distinct subset of diabetes characterized by severe insulin‐resistant diabetes." (PMID 37853916, 2024). "In addition, the protein phosphatase Mg2+/Mn2+-dependent 1A (PPM1A), which dephosphorylates Ser-273 of PPARγ can restore dysregulated genes involved in diabetes progression in obese mice." (PMID 38735390, 2024). "Furthermore, this protective anti-degenerative effect of PPARγ activation has been demonstrated to persist in front of pro-degenerative co-morbidities like metabolic syndrome and diabetes." (PMID 39175545, 2024). "In addition, PPAR agonists (such as fibrates for PPARα and glitazone for PPARγ) have been used for decades to treat dyslipidemia and diabetes." (PMID 38925330, 2024).
diabetes (continued). "Moreover, troglitazone, an insulin-sensitizing drug that is prescribed for treating type 2 diabetes mellitus, is a synthetic PPARγ agonist that interferes with NF-κB activity and exerts its anti-inflammatory effects through the activation of PPARγ." (PMID 36875108, 2023). "Thus, the combination of sEH inhibition and PPARγ agonism reduces side effects while increasing efficacy for hypertension and diabetes." (PMID 37427406, 2023). "PPARγ may be activated by thiazolidinediones (TZDs) (synthetic activators that are sometimes used to treat type 2 diabetes mellitus)." (PMID 38003402, 2023). "Activation of the PPARγ pathway in MPs is generally considered to be antiinflammatory, and there is consensus for a beneficial effect of systemic PPARγ agonist treatment in a wide range of diseases, including diabetes and its comorbidities." (PMID 37781924, 2023). "Among the natural agonists of PPARγ are the polyunsaturated fatty acids, glucocorticoids, and insulin, with thiazolidinedione also having a high affinity for PPARγ, which exercise their therapeutic effects in type 2 diabetes mellitus." (PMID 36986146, 2023). "Future modifications based on diosmin as the lead compound may provide more attractive candidates against diabetes via blocking PPARγ S273 phosphorylation." (PMID 36841479, 2023). "These antagonists maintain robust antidiabetic activity in rodent models of diabetes and may provide a safe alternative to targeting PPARγ for the therapeutic intervention in insulin resistance and T2D." (PMID 37189440, 2023). "PPARγ activity has been increased in human primary trophoblast cells exposed to hyperglycemia and in the placentas of pregnant female mice with streptozotocin-induced diabetes mellitus." (PMID 38003402, 2023). "PPARs involve three subtypes (PPARα; NR1C1, PPARβ; NR1C2, and PPARγ; NR1C3) that control insulin sensitivity, resistance, and lipid homeostasis, making them valid targets for alleviating metabolic syndrome, hyperlipidemia, and diabetes." (PMID 37893218, 2023). "(ii) PPARγ levels are related to osteoporosis in diabetes patients." (PMID 36951483, 2023). "Therefore, a deeper understanding of PPARγ and its activation is essential for the development of noveltherapeutic strategies to combat diabetes, metabolic syndrome, and cardiovascular diseases." (PMID 37901293, 2023). "In people with diabetes, there were 2 studies which evaluated the yield for PPARG or LMNA etiology." (PMID 37794142, 2023). "This may suggest that S-nitrosylation of PPARγ may be a “bad” modification in diabetes treatment, increases adipocyte production, and impairs insulin sensitivity." (PMID 36551260, 2022). "Since the use of PPARγ full agonists in the treatment of type-2 diabetes mellitus has been linked to several negative side effects, the development of new alternative candidates as PPARγ ligands has gotten a lot of attention in recent years." (PMID 36297575, 2022). "Peroxisome proliferator-activated receptor (PPARγ) agonists, such as thiazolidinediones (TZDs), used in the treatment of diabetes, have also been reported to show unwanted side effects, including weight gain, cardiovascular disease, fluid retention, bone fracture, and bladder cancer." (PMID 35563411, 2022). "Also, fucosterol (a triterpenoid), umbelliferone (a coumarin), and chelerythrine (an alkaloid) demonstrated PPARγ activation in remediation of liver injury, liver fibrosis, and diabetes in animal models, respectively." (PMID 36092543, 2022). "In addition to diabetes treatment, PPARG activation can also decrease renal fibrosis and inflammation, reduce salt and water retention in the renal tubules to prevent swelling of the stromal cells and reduce damage to kidney cells (Yki-Järvinen, 2004)." (PMID 35265101, 2022).
diabetes (continued). "The activation of MAPK can activate the downstream “peroxisome proliferators-activated receptor gamma” (PPARγ) to induce the apoptosis of vascular smooth muscle cells, and inactivation of the MAPK/PPARγ signaling alleviates diabetes-induced ED via suppression of the corpus cavernosal cell apoptosis." (PMID 36210810, 2022). "Hence, the PPARG agonist is important for increasing glucose tolerance by boosting insulin sensitivity and the functionality of beta cells in diabetics." (PMID 35207564, 2022). "Also, it has been shown that the peroxisome proliferator-activated receptor gamma (PPAR-γ) pathway is affected by the punicic acid continent of pomegranate juice which in turn, modulates glucose uptake and diabetes-induced inflammation." (PMID 35581639, 2022). "S. tamariscina, in particular, has been reported to possess antioxidant, anti-hyperglycemic, and antihyperlipidemic effects in diabetes by enhancing peroxisome proliferator-activated receptor gamma (PPARγ) expression in AT and insulin receptor substrate 1 (IRS-1) expression in liver and muscle." (PMID 35454963, 2022). "Collectively, our results shed light on the mechanisms behind the glucose-lowering effects of MLF, suggesting that morusin and kuwanon C might be selective PPARγ modulators and possess broad prospects as new drugs or leads against diabetes." (PMID 36278175, 2022). "Pparγ, when stimulated by TZDs, a class of Pparγ ligands, controls glucose homeostasis in diabetes." (PMID 33804020, 2021). "In addition, PPARγ agonists, namely, pioglitazone and rosiglitazone, are the currently approved drugs for the management of hyperglycaemia in patients with type 2 diabetes mellitus." (PMID 34639224, 2021). "Furthermore, apart from being implicated in the pathophysiology of both dyslipidemia and diabetes, PPARγ activation through its endogenous ligand 15d-PGJ2 regulates inflammation, angiogenesis, and apoptosis in the retinal pigmented endothelium." (PMID 33828528, 2021). "Pioglitazone is a selective PPARγ agonist used to treat diabetes." (PMID 33822489, 2021). "Pharmacological control of the PPARγ pathway and its regulators by both TZDs and statins, respectively used for treating diabetes and dyslipidemia, illustrates the molecular interplay among pathways involved in the pathogenesis and therapy of these two disease states." (PMID 33828528, 2021). "It was suggested that interfering with docking of THRAP3 on PPARγ could be a strategy to screen for compounds for diabetes treatment." (PMID 34526909, 2021). "Although PPARγ activation promotes antioxidant response and promotes the expression of antioxidant enzymes and NO product in ECs, PPARγ receptors are downregulated in the diabetic eye and their suppression is involved in the pathogenesis of DR." (PMID 33013692, 2020). "PPARγ is an important transcription factor that plays substantial roles in the regulation of glucose and lipid metabolism which is also a target of pharmacological therapy of diabetes." (PMID 32596392, 2020). "Adiponectin may mediate the beneficial effects of PPARγ agonists for the treatment of diabetes, as it is an insulin-sensitizing adipokine that affects hepatic glucose output and decreases triglyceride content in the liver and muscle." (PMID 31918918, 2020). "PPARγ agonists improve insulin sensitivity and treat complications of diabetes." (PMID 32031298, 2020). "In addition, it was reported that PPARγ was an important receptor in the treatment of diabetes, and its activation reduced hyperglycemia by increasing sensitivity to peripheral insulin." (PMID 32265835, 2020). "Studying this interplay between SREBP, PPARγ and steroid hormone signaling will shed light on to which extent adaptation of intestinal size and lipid metabolism contribute to pathophysiological conditions like diabetes." (PMID 32773037, 2020). "Thus, we tested pharmacological activation of Eip75B/PPARγ with the established agonist Pioglitazone, a drug used in Diabetes mellitus treatment." (PMID 32773037, 2020).
diabetes (continued). "In addition, 10- and 12-(Z,E)-HODEs, which we previously proposed as biomarkers for early-stage diabetes, exerted PPARγ agonist activity." (PMID 32266936, 2020). "PPARα and PPARγ are famous targets for treating diabetes, especially PPARγ." (PMID 32028670, 2020). "Thus, PPARγ is a good therapeutic target for type 2 diabetes mellitus, as well as other metabolic diseases including obesity and atherosclerosis." (PMID 31581474, 2019). "PPARγ was originally studied for its role in lipid and glucose metabolism, with its preferential ligands, the thiazolidinediones, currently being widely used in the pharmacological management of type 2 diabetes mellitus (e.g., pioglitazone)." (PMID 30669473, 2019). "Thus, PPARγ is one of the most effective pharmacological targets for type 2 diabetes mellitus as well as other metabolic diseases, such as obesity and atherosclerosis." (PMID 31371757, 2019). "Numerous studies confirmed that independent of their metabolic actions, RSG as a PPARγ agonist has a protective effect against oxidative stress caused by high glucose in diabetes and hypoperfusion." (PMID 31470514, 2019). "The ability of Tβ4 to induce mtROS is reminiscent of the activity of pioglitazone, a peroxisome proliferator–activated receptor γ (PPARγ) agonist, currently approved for the treatment of diabetes mellitus type 2 and recently proposed as a therapeutic molecule for CGD." (PMID 31719116, 2019). "Exercise-induced decrements of chemerin/CMKLR1 in the diabetes rats were mediated by PPARγ." (PMID 30873215, 2019). "Furthermore, TDQ reversed diabetes-induced decrease in the mRNA and protein expression of PPARγ and elevation in the mRNA and protein levels of DGAT2 in the liver." (PMID 31019978, 2019). "Since PPARγ is involved in carbohydrate metabolism, adipogenesis, and inflammation, PPARγ agonists have been widely used in the management of diabetes and oxidative stress-related diseases, and its antineoplastic effect against pancreatic cancer has been further confirmed in a series of studies." (PMID 29483923, 2018). "The activation of the AMP-activated protein kinase (AMPK) system and a role of the α- and γ-peroxisome proliferator-activated receptors (PPARα and PPARγ) have been hypothesized as possible mechanisms of action for M. charantia in diabetes treatment." (PMID 29300317, 2018). "Moreover, the PPARγ agonists have been widely used in type 2 diabetes mellitus, such as thiazolidinone drugs (TZDs)." (PMID 29862294, 2018). "PPARγ has, therefore, long been considered an attractive drug target for the treatment of diabetes." (PMID 29160030, 2018). "TZDs, as PPARγ agonists, are increasingly being used to counteract the effects of diabetes by regulating the transcription of insulin-responsive genes, thereby enhancing insulin sensitivity in adipose tissue, skeletal muscle and liver to help reduce plasma glucose and insulin." (PMID 30060458, 2018). "The peroxisome proliferator-activated receptor γ (PPARγ) is generally regarded as a molecular target for the thiazolidinedione class of anti-diabetic drugs, as it plays a key role in the generation and development of diabetes mellitus." (PMID 29473866, 2018). "TZDs, synthesized PPARγ agonists, are used in controlling blood sugar in patients with diabetes." (PMID 29932104, 2018). "Gout patients with metabolic comorbidities such as type 2 diabetes mellitus and other manifestations of the metabolic syndrome may therefore strongly profit from PPARγ activation also in terms of reduced gout." (PMID 30202096, 2018). "For example, PPARγ agonists have been applied to treat hyperlipidemia, hyperglycemia, diabetes." (PMID 30034368, 2018). "Interestingly, telmisartan attenuated diabetes-induced increases in BBB permeability through PPARγ activation to improve diabetes-induced cognitive decline." (PMID 29543776, 2018). "For example, the PPARG gene plays a role in diabetes genetics and therapy." (PMID 30577445, 2018).